RPL27 (ribosomal protein L27)
Description:
Component of the large ribosomal subunit. Required for proper rRNA processing and maturation of 28S and 5.8S rRNAs.
Synonyms: L27; eL27; DBA16
Tractability: Small molecule: an approved drug acts on it; a structure with a bound ligand is known; a high-quality ligand is known. PROTAC: ubiquitination databases record sites on it; its protein half-life has been measured; a small molecule that binds it is known. Other modalities: a drug acting on it is in phase 2 or 3 trials.
Target class: Other cytosolic protein
Gene: Protein-coding gene on chromosome 17 (42,998,273 to 43,002,973, forward strand). Ensembl gene ENSG00000131469.
Subcellular location: Cytoplasm, cytosol; Cytoplasm; Rough endoplasmic reticulum
Subcellular location (Human Protein Atlas): Nucleoli; Nucleoplasm
Pathways (Reactome):
Metabolism of proteins: Eukaryotic Translation Termination; Formation of a pool of free 40S subunits; GTP hydrolysis and joining of the 60S ribosomal subunit; L13a-mediated translational silencing of Ceruloplasmin expression; PELO:HBS1L and ABCE1 dissociate a ribosome on a non-stop mRNA; Peptide chain elongation; Ribosome Quality Control (RQC) complex extracts and degrades nascent peptide; SRP-dependent cotranslational protein targeting to membrane; ZNF598 and the Ribosome-associated Quality Trigger (RQT) complex dissociate a ribosome stalled on a no-go mRNA
Metabolism of RNA: Major pathway of rRNA processing in the nucleolus and cytosol; Nonsense Mediated Decay (NMD) enhanced by the Exon Junction Complex (EJC); Nonsense Mediated Decay (NMD) independent of the Exon Junction Complex (EJC)
Cellular responses to stimuli: Response of EIF2AK4 (GCN2) to amino acid deficiency
Developmental Biology: Regulation of expression of SLITs and ROBOs
Disease: Viral mRNA Translation
Metabolism: Selenocysteine synthesis
Gene Ontology:
Molecular function: protein binding; RNA binding; structural constituent of ribosome
Biological process: rRNA processing; cytoplasmic translation; negative regulation of myoblast fusion; spermatogenesis; striated muscle contraction; translation; response to aldosterone
Cellular component: cytosolic large ribosomal subunit; cytosolic ribosome; extracellular exosome; focal adhesion; membrane; nucleolus; nucleoplasm; nucleus; ribonucleoprotein complex; cytoplasm; cytoplasmic side of rough endoplasmic reticulum membrane; cytosol; ribosome; rough endoplasmic reticulum; synapse
Genetic constraint (gnomAD): Loss-of-function variants: 0 observed, 11.56 expected, observed/expected ratio (o/e) 0, 90% interval 0 to 0.26. The upper end of that interval is the gene's LOEUF score, 0.26, which puts it in group 1 of 6, group 1 being the genes least tolerant of losing a copy. Missense variants: 126 observed, 173.21 expected, observed/expected ratio (o/e) 0.73, 90% interval 0.63 to 0.84. Synonymous variants: 72 observed, 61.93 expected, observed/expected ratio (o/e) 1.16, 90% interval 0.96 to 1.41.
Homologues: Orthologues: chimpanzee RPL27 (100% identical), dog RPL27 (100% identical), macaque RPL27 (100% identical), mouse Rpl27 (100% identical), pig RPL27 (100% identical), rabbit RPL27 (100% identical), rat Rpl27 (100% identical), zebrafish rpl27 (96% identical), tropical clawed frog rpl27 (89% identical), Caenorhabditis elegans rpl-27 (69% identical), Drosophila melanogaster RpL27 (62% identical).
Diseases named in the same sentence as RPL27 in open-access papers:
RPL27 is named in the same sentence as 24 diseases in open-access papers, as found by Europe PMC text mining. Sharing a sentence is not in itself a finding about the gene and the disease. The quoted sentences say what the papers report.
ZIKV infection (2 papers, 2021 to 2025). "Ribosomal proteins RpL23 and RpL27 are critical for ZIKV infection, and they can be directly regulated by the JH-receptor complex." (PMID 34061577, 2021). "In the present study, 73% of ribosomal protein genes in A. aegypti were upregulated after ZIKV infection, and silencing of RpL23 and RpL27 significantly attenuated ZIKV infection." (PMID 34061577, 2021). "Silencing of RpL23 and RpL27, two ribosomal large subunit genes, increased mosquito resistance to ZIKV infection." (PMID 34061577, 2021). "In addition, RNA interference (RNAi) silencing of RpL23 and RpL27, two JH-regulated ribosomal large subunit genes, suppressed ZIKV infection in A. aegypti." (PMID 34061577, 2021). "Moreover, the upregulated expression of RpL23 and RpL27 could facilitate the translation of viral proteins and promotes ZIKV infection in Aedes aegypti." (PMID 40806613, 2025). "Most of the salivary glands from RpL27 dsRNA-treated mosquitoes were negative for ZIKV infection compared to those from the EGFP group." (PMID 34061577, 2021).
breast carcinoma (1 paper, 2025). "Following identification of optimal RGs, we aimed to evaluate combined use of RPLP1 and RPL27 for normalisation of gene transcription in a panel of normoxic and hypoxic breast cancer cell lines." (PMID 39838295, 2025). "For the study of hypoxia-mediated alterations in gene expression between MCF-7, T-47D, MDA-MB-231 and MDA-MB-468 breast cancer cell lines, GeNorm recommended the combined use of RPL27 and RPLP1." (PMID 39838295, 2025). "Thus, combination of RPLP1 and RPL27 as RGs is suitable for normalising gene expression in this panel of normoxic and hypoxic breast cancer cell lines." (PMID 39838295, 2025). "For the TNBC group, RPL30 was placed first by all programs, apart from GeNorm which recommended RPL27 and RPLP1, the same as for all four breast cancer cell lines." (PMID 39838295, 2025). "Our findings identify RPLP1, or RPLP1 in combination with RPL27, as optimal RGs for analysis of hypoxia-mediated gene transcription in MCF-7, T-47D, MDA-MB-231 and MDA-MB-468 breast cancer cell lines." (PMID 39838295, 2025). "Our identification of RPLP1 and RPL27 as robust RGs in this panel of hypoxic Luminal A and TNBC cell lines provides a valuable resource for future studies investigating important transcriptional changes occurring during breast cancer progression." (PMID 39838295, 2025).
diabetes (1 paper, 2012). "CYCA, GAPDH and RPL27 were invariably identified as the most stable genes in our cohort based on their smoking, PVD, diabetes, hypertension, MS and medication status." (PMID 22511915, 2012).
hepatocellular carcinoma (1 paper, 2020). A malignant tumor that arises from hepatocytes. "The mRNA level of RPS8, RPL12, RPL23A, RPL27, and RPL30 was detected as upregulated in hepatocellular carcinoma tissues and cell lines." (PMID 33584809, 2020).
liver cancer (1 paper, 2025). An epithelial or non-epithelial malignant neoplasm that arises from the liver. "Further supporting the role of RPL27 in tumour cell proliferation, knockdown of RPL27 expression in SNU449 and HepG2 liver cancer cell lines resulted in increased expression of the pro-apoptotic proteins Bax and caspase-3 and decreased expression of the apoptosis inhibitor Bcl-2." (PMID 40940922, 2025).
Obesity (1 paper, 2012). Accumulation of substantial excess body fat. "In conclusion, CYCA, GAPDH and RPL27 were identified as the most stable reference genes common to Genorm, Normfinder and Bestkeeper algorithms for studies involving human EAT, not only in context of obesity but also under a variety of other conditions." (PMID 22511915, 2012).
viral infection (1 paper, 2021). "After viral infection, the midgut and the salivary gland from RpL23 and RpL27 dsRNA-treated mosquitoes were dissected for virus detection by qPCR." (PMID 34061577, 2021).
infection (3 papers, 2021 to 2025). The state of being infected such as from the introduction of a foreign agent such as serum, vaccine, antigenic substance or organism. "Upon infection, the expression of mRpS11, RpL23, and RpL27 was significantly upregulated in midgut 1 dpi or fat body 7 dpi." (PMID 34061577, 2021). "During the early stages of infection, Zika virus (ZIKV) regulates the expression of some ribosomal protein genes (RpL23 and RpL27) through the JH-Met-Tai signalling pathway." (PMID 40806613, 2025).
tumor (3 papers, 2018 to 2025). "Increased expression of various ribosomal proteins (rpS8, rpL12, rpL23a, rpL27, and rpL30) have been associated with tumor growth." (PMID 32973493, 2020). "Finally, we validated their expression using qPCR in an additional set of tumor:matched normal samples that resulted in five genes (RPL30, RPL27, PSMC5, MTCH1, and OAZ1), out of which RPL30 and RPL27 were most stable and were abundantly expressed across the tissues." (PMID 30128175, 2018).
head and neck tumor (1 paper, 2018). "Our data suggest that RPL30 or RPL27 in combination with either PSMC5 or MTCH1 or OAZ1 can be used as a minimal set of control genes in head and neck tumor gene expression studies." (PMID 30128175, 2018).
kidney diseases (1 paper, 2024). "This suggests that TUBB6 may be used as a potential biomarker to compare two related kidney diseases (FSGS and MCD), and TUBB6, RPL27, and PFDN5 can be used as potential biomarkers to detect FSGS." (PMID 39519211, 2024).
RPL27 also shares sentences with these, for which no sentence is quoted: cancer (3 papers); Diamond-Blackfan anemia (2); Chlamydial disease (1); dental caries (1); focal segmental glomerulosclerosis (1); glomerulosclerosis (1); head and neck squamous cell carcinoma (1); Hypertension (1); Infertility (1); Neonatal sepsis (1); neurological disorders (1); pancreatic cancers (1); Stroke (1).